WDR37 (WD repeat domain 37)
Description:
Required for normal ER Ca2+ handling in lymphocytes. Together with PACS1, it plays an essential role in stabilizing peripheral lymphocyte populations.
Synonyms: KIAA0982; NOCGUS
Tractability: PROTAC: ubiquitination databases record sites on it; its protein half-life has been measured.
Gene: Protein-coding gene on chromosome 10 (1,049,265 to 1,160,991, forward strand). Ensembl gene ENSG00000047056.
Subcellular location: Cytoplasm; Nucleus
Subcellular location (Human Protein Atlas): Intermediate filaments
Gene Ontology:
Molecular function: protein binding
Biological process: lymphocyte homeostasis
Cellular component: cytoplasm; nucleus
Genetic constraint (gnomAD): Loss-of-function variants: 17 observed, 60.33 expected, observed/expected ratio (o/e) 0.28, 90% interval 0.19 to 0.42. The upper end of that interval is the gene's LOEUF score, 0.42, which puts it in group 1 of 6, group 1 being the genes least tolerant of losing a copy. Missense variants: 452 observed, 665.56 expected, observed/expected ratio (o/e) 0.68, 90% interval 0.63 to 0.73. Synonymous variants: 241 observed, 266.11 expected, observed/expected ratio (o/e) 0.91, 90% interval 0.81 to 1.01.
Gene-disease validity (ClinGen):
ClinGen rates the evidence that WDR37 causes each of these diseases.
neurooculocardiogenitourinary syndrome (autosomal dominant): Definitive. An autosomal dominant multisystem disorder characterized by significant neurological impairment with structural brain defects and seizures, poor feeding, poor postnatal growth, ocular anomalies, dysmorphic facial features, and variable skeletal, cardiac and genitourinary defects.
Homologues: Orthologues: chimpanzee WDR37 (99% identical), macaque WDR37 (98% identical), rabbit WDR37 (97% identical), rat Wdr37 (97% identical), mouse Wdr37 (97% identical), dog WDR37 (95% identical), pig WDR37 (94% identical), tropical clawed frog wdr37 (91% identical), guinea pig WDR37 (88% identical), zebrafish wdr37 (84% identical), Drosophila melanogaster Wdr37 (49% identical), Caenorhabditis elegans wdr-37 (42% identical). Paralogues in human: WDR12 (21% identical).
Diseases named in the same sentence as WDR37 in open-access papers:
WDR37 is named in the same sentence as 20 diseases in open-access papers, as found by Europe PMC text mining. Sharing a sentence is not in itself a finding about the gene and the disease. The quoted sentences say what the papers report.
autism spectrum disorder (1 paper, 2024). A spectrum of developmental disorders that includes autism, and Asperger syndrome. "PACS1, PACS2, and WDR37 variants are associated with multisystemic syndromes and neurodevelopmental disorders characterized by intellectual disability, seizures, developmental delays, craniofacial abnormalities, and autism spectrum disorder." (PMID 39031646, 2024).
autosomal recessive spinocerebellar ataxia 30 (1 paper, 2025). "Among these, three were OMIM-annotated:ZMYND11 (associated with autosomal dominant intellectualdevelopmental disorder 30 [AD]), WDR37 (linked toneurooculo-cardiogenitourinary syndrome [AD]), PITRM1(implicated in autosomal recessive spinocerebellar ataxia 30[AR])." (PMID 40995453, 2025).
cervical carcinoma (1 paper, 2013). A carcinoma arising from either the exocervical squamous epithelium or the endocervical glandular epithelium. "The effect of ectopic expression of SORBS2, TLR3, CYP4V2, FBXO18, IL15RA, WDR37 and DIP2C on the cell phenotype, in particular senescence, was investigated in primary cells, HPV-immortalized cells and cervical carcinoma cells." (PMID 24165198, 2013).
epilepsy (1 paper, 2023). A brain disorder characterized by episodes of abnormally increased neuronal discharge resulting in transient episodes of sensory or motor neurological dysfunction, or psychic dysfunction. "Previously, genes containing the WD repeat domains such as WDR37 and WDR45 have been reported to be associated with epilepsy." (PMID 36514184, 2023).
esophageal squamous cell carcinoma (1 paper, 2017). Esophageal squamous cell carcinoma (ESCC) is a type of esophageal carcinoma (EC) that can affect any part of the esophagus, but is usually located in the upper or middle third. "Furthermore, a positive correlation between hsa_circ_0004277 and WDR37 was observed in all the AML patients at different stages, which was consistent with the circRNA report concerning esophageal squamous cell carcinoma." (PMID 28282919, 2017).
Lissencephaly (1 paper, 2019). A spectrum of malformations of cortical development caused by insufficient neuronal migration that subsumes the terms agyria, pachygyria and subcortical band heterotopia. "There are no direct evidences for ASDs development and WDR37—however, recently, it has been demonstrated that WDR47 shares functional characteristics with PAFAH1B1, which causes lissencephaly." (PMID 31323926, 2019).
pancreatic cancer (1 paper, 2023). "Notably, the only independent protective factor WDR37 was low expression in pancreatic cancer, and the only independent risk factor NUP37 was high expression in pancreatic cancer." (PMID 38304253, 2023). "In order to explore the potential mechanism of the effect of WDR37 on the prognosis of pancreatic cancer, WDR37 was overexpressed in pancreatic cancer cell line SW1990 to identify the binding proteins by immunoprecipitation-mass spectrometry." (PMID 38304253, 2023). "The tissue array of clinical samples was assessed to verify the expression characteristics and prognosis effect of WDR37 on pancreatic cancer patients." (PMID 38304253, 2023). "Immunohistochemistry showed that the expression of WDR37 in pancreatic cancer tissues was significantly lower than that in paracancerous tissues, and the expression of WDR37 in normal pancreatic tissues was significantly higher than that in pancreatic cancer tissues." (PMID 38304253, 2023). "WDR37 might be an important tumor suppressor gene in pancreatic cancer and the possible mechanism was revealed in vitro." (PMID 38304253, 2023). "In conclusion, WDR37 may inhibit the progression of pancreatic cancer and promote tumor immune response by promoting the degradation of TCP1 protein in pancreatic cancer." (PMID 38304253, 2023). "WDR37 might be the most prognostic E3 ubiquitin ligase in pancreatic cancer, and the clinical cohort analyses suggested a tumor‐suppressive role." (PMID 38304253, 2023). "In addition, although this study suggested that WDR37 was a strong tumor suppressor for pancreatic cancer, further studies are needed to reveal its specific molecular mechanism." (PMID 38304253, 2023). "Furthermore, functional cluster analysis and clinical decision analysis suggested that WDR37 might be the most prognostic E3 ubiquitin ligase in pancreatic cancer." (PMID 38304253, 2023). "At the same time, WDR37, the main gene in E3PMP signature, can be used as the most prognostic E3 ubiquitin ligase in the treatment of pancreatic cancer." (PMID 38304253, 2023).
neurodevelopmental disorder (2 papers, 2022 to 2024). A behavioral and cognitive disorder with onset during the developmental period that involves impaired or aberrant development of intellectual, motor, or social functions. "Since 2012, when PACS1-NDD was first characterized, deep phenotyping analysis has allowed us to establish a potential relationship with other neurodevelopmental disorders, such as the PACS2 or Wdr37 syndromes." (PMID 36077045, 2022).
tumor (2 papers, 2021 to 2023). "In summary, WDR37 may play an anti-tumor role by mediating the degradation of TCP1 complex through K48 ubiquitin modification." (PMID 38304253, 2023). "The results of functional analysis, in vitro experiments and clinical cohort studies suggested a tumor‐suppressive role of WDR37, and the mechanism may be related to the role of TCP1 complex." (PMID 38304253, 2023). "The results of functional analysis and in vitro experiments indicated that WDR37 may promote the degradation of TCP1 complex to inhibit tumor and improve immune cell infiltration." (PMID 38304253, 2023).
cancer (1 paper, 2023). A tumor composed of atypical neoplastic, often pleomorphic cells that invade other tissues. "Among these, AKAP12 and ZNF483 emerged as the most differentially down-regulated coding circRNAs whereas AFTPH, CHST15 and WDR37 were differentially up-regulated in the pan-cancer RNA-Seq dataset." (PMID 37106694, 2023). "Conversely, the circRNAs encoded by CHST15, WDR37, and SOX13, and their role in cancer have been previously delineated in the literature." (PMID 37106694, 2023).
neurological disorder (1 paper, 2025). "Recent work revealed strong similarities between PACS1-NDD, PACS2 syndrome and the recently identified WDR37 syndromic neurological disorder." (PMID 39999877, 2025).
WDR37 also shares sentences with these, for which no sentence is quoted: Bardet-Biedl syndrome (1 paper); chronic kidney disease (1); congenital diaphragmatic hernia (1); developmental delays (1); Duane retraction syndrome (1); Intellectual disability (1); mammary tumors (1); Seizure (1); Verheij syndrome (1).